RN7SKP217 (RN7SK pseudogene 217)
Gene: Miscellaneous RNA gene on chromosome 15 (76,736,641 to 76,736,980, forward strand). Ensembl gene ENSG00000201510.
Homologues: Orthologues: chimpanzee 7SK (100% identical). Paralogues in human: 7SK (75% identical), RN7SKP118 (71% identical), RN7SKP294 (71% identical), RN7SKP133 (71% identical), RN7SKP9 (71% identical), RN7SKP162 (70% identical), RN7SKP184 (70% identical), RN7SKP187 (70% identical), RN7SKP203 (70% identical), RN7SKP62 (70% identical), RN7SKP90 (70% identical), RN7SKP124 (69% identical), and 284 more.